CT47A4 (cancer/testis antigen family 47 member A4)
Synonyms: CT47.4
Gene: Protein-coding gene on chromosome X (120,967,886 to 120,971,208, reverse strand). Ensembl gene ENSG00000230594.
Subcellular location (Human Protein Atlas): Nucleoli
Homologues: Orthologues: macaque CT47B1 (77% identical). Paralogues in human: CT47A1 (100% identical), CT47A10 (100% identical), CT47A11 (100% identical), CT47A12 (100% identical), CT47A2 (100% identical), CT47A3 (100% identical), CT47A5 (100% identical), CT47A6 (100% identical), CT47A7 (100% identical), CT47A8 (100% identical), CT47A9 (100% identical), CT47B1 (86% identical), and 1 more.
Diseases named in the same sentence as CT47A4 in open-access papers:
CT47A4 is named in the same sentence as 1 disease in open-access papers, as found by Europe PMC text mining. Sharing a sentence is not in itself a finding about the gene and the disease. The quoted sentences say what the papers report.
cancer (1 paper, 2022). A tumor composed of atypical neoplastic, often pleomorphic cells that invade other tissues. "In anal swabs, we found that two genes located on the X chromosome were positively correlated with disease severity, namely, CT47A8 and CT47A4, both of which belong to the cancer/testis antigen family." (PMID 36118230, 2022).